PTH (parathyroid hormone)
Diseases named in the same sentence as PTH in open-access papers (continued):
Sharing a sentence is not in itself a finding about the gene and the disease.
Hypercalcemia (continued). "He developed severe hypercalcemia with free ionized calcium reaching 1.81 mmol/L (total calcium 3.33 mmol/L), concurrent with peaks in CEA and PTH levels." (PMID 33413267, 2021). "Gender,hypercalcemia-related symptoms at onset, and, most importantly, occurrence ofsignificant and permanent loss of renal function were seen as the main similarities.However, our patients were older, presented non-suppressed PTH, and one of them didnot have elevated calcitriol levels." (PMID 32779690, 2021). "Primary hyperparathyroidism is a common endocrine disorder characterized by elevated blood concentration of parathyroid hormone (PTH) and hypercalcemia, usually due to a benign overgrowth of parathyroid tissue." (PMID 34034731, 2021). "Although PTH stimulates an increase in tubular magnesium reabsorption in patients with PHPT, the direct effect of hypercalcemia on tubular magnesium reabsorption is the opposite." (PMID 34416890, 2021). "In January 2019 (1 year after the surgery), the patient was hospitalized in our institution for symptomatic hypercalcemia, with an ACC level of 3.5 mmol/l and a concomitant PTH level of 724 ng/l (reference range 10-70 ng/l)." (PMID 35173680, 2021). "Parathyroid hormone (PTH) serum concentration is elevated, or within normal limits but inappropriate considering the presence of hypercalcemia." (PMID 33839893, 2021). "Intact-parathyroid hormone (PTH) level was high (273 pg/mL) and hypercalcemia (Ca, 12.1 mg/dL) were observed." (PMID 34384417, 2021). "Although serum Ca, P and intact parathyroid hormone (PTH) levels tend to normalize over the time after transplantation, hypercalcemia has been reported in 5%–66% of recipients." (PMID 32913586, 2020). "It is characterized by excessive secretion of parathyroid hormone (PTH) from the parathyroid glands, leading to hypercalcemia, hypercalciuria and hypophosphatemia." (PMID 32331456, 2020). "Primary hyperparathyroidism (PHPT) is a common endocrine disease characterized by inappropriate excessive secretion of parathyroid hormone (PTH) and consequent hypercalcemia." (PMID 30832348, 2019). "A typical presentation and severe hypercalcaemia in an infant born to consanguineous parents were highly suggestive of NHSPT, and further testing which revealed high PTH levels and typical radiological features was highly suggestive in our patient." (PMID 32120468, 2019). "Investigations revealed severe hypercalcaemia, low serum phosphorus, normal alkaline phosphatase (ALP), high serum intact parathormone (PTH) with a sufficient Vitamin-D level." (PMID 32120468, 2019). "The prevalence of hypercalcemia and hyperphosphatemia was only 6.7 and 9.7% in CKD and 2.3 and 4.9% in CKD-T patients, respectively, while elevated i-PTH levels were present in 76% of CKD and 48% of CKD-T patients." (PMID 28795324, 2018). "Thus, Gna11+/195G mice had mild hypercalcemia in association with normal plasma PTH concentrations; they also had no alterations in the plasma concentrations of phosphate and creatinine, or in alkaline phosphatase activity, which is consistent with the reported phenotype of FHH2 patients." (PMID 29046478, 2017). "Those complications include high levels of parathyroid hormone (PTH) and mineral abnormalities such as hypercalcemia and hyperphosphatemia." (PMID 27071541, 2016). "In the presented patient, HPP was considered with onset before 6 months of age, phenotypic appearance, skeletal deformities, hypercalcemia, remarkably low level of ALP, and low PTH level." (PMID 27086862, 2016). "In patients with VDI, hypercalcemia, normal or high serum phosphorus levels, normal or low levels of ALP, high levels of 25-OHD, low serum of PTH, and high urinary calcium/creatinine ratio are usually present." (PMID 27478669, 2016).
Hypercalcemia (continued). "In CKD patients, this hypercalcemia causes a decrease in the PTH level, distinguishing it from tertiary hyperparathyroidism, though PTH may not be totally suppressed, the way it is seen in PTH-independent hypercalcemia in non-CKD patients." (PMID 27683096, 2016). "Parathyroid adenomas usually come to clinical attention due to overexpression of parathyroid hormone (PTH), which leads to hypercalcemia." (PMID 26610856, 2015). "Finally and rarely, PTH may be secreted, leading to hypercalcemia through the actions of PTH." (PMID 26328223, 2014). "Parathyroid cystic adenomas are often misdiagnosed as thyroid cysts, even in the case of elevated parathyroid hormone (PTH) levels, and especially with asymptomatic hypercalcemia." (PMID 25379182, 2014). "Later on, Sorscher described a patient with severe hypercalcemia and a NSGCT with a high PTHrP and a normal PTH that returned to normal values after chemotherapy." (PMID 24721620, 2014). "Thus, adult male and female Crh−120/+ mice, aged 8–12 weeks, were hypercalcemic, and this was associated with significantly reduced plasma PTH concentrations, indicating that the hypercalcemia was not due to hyperparathyroidism associated with parathyroid tumors." (PMID 24302625, 2014). "Thus, the CS mice have a reduction in osteoblasts that is associated with decreased rates of bone formation and mineral apposition, and this lack of bone calcium deposition may account for the observed hypercalcemia, decreased circulating PTH concentrations, and hypercalciuria." (PMID 24302625, 2014). "Mice with homozygous deletion of the calcium-sensing receptor (CaR) mimic the syndrome of neonatal severe hyperparathyroidism (NSHPT) in humans with very high circulating parathyroid hormone (PTH) and severe life-threatening hypercalcemia." (PMID 21966280, 2011). "Familial hypocalciuric hypercalcemia (FHH) is a rare autosomal dominant disorder of calcium homeostasis characterized by mild hypercalcemia, non-suppressed parathyroid hormone (PTH), and hypocalciuria." (PMID 42291983, 2026). "Primary hyperparathyroidism (PHPT) is a metabolic disorder characterized by hypercalcemia with elevated or nonsuppressed parathyroid hormone (PTH) levels." (PMID 41568160, 2026). "Non-parathyroid hormone (PTH)-mediated hypercalcemia has diverse etiologies, including granulomatous disorders such as sarcoidosis, in which extrarenal 1-α-hydroxylase activity leads to excess production of 1,25-dihydroxyvitamin D (1,25(OH)2D)." (PMID 41756472, 2026). "In case of hypercalcemia, PTH in circulation would be suppressed (negative feedback), leading to decreased Ca2+ and increased phosphate reabsorption at the renal tubular level." (PMID 41503412, 2026). "Similar findings are revealed in numerous studies including PHPT patients without hypercalcemia/PTH-related symptoms or organ-specific symptoms." (PMID 40177730, 2025). "This condition should be suspected in women presenting with unexplained hypercalcemia, suppressed PTH, and a negative secondary workup for malignancy, granulomatous disease, and contributory medications." (PMID 41377203, 2025). "This variation in opinion is important, given that a recent meta-analysis demonstrated that cinacalcet could normalize hypercalcemia in 90% of patients with PHPT, significantly reduce PTH levels, and increase serum phosphate levels." (PMID 39876875, 2025). "The mechanism responsible for hypercalcaemia in granulomatous diseases, such as sarcoidosis or tuberculosis, occurs due to extrarenal calcitriol production independent of PTH by activated mononuclear cells in the lungs and lymph nodes." (PMID 39903584, 2025). "This case highlights the importance of using parathyroid hormone and calcitriol levels to distinguish between parathyroid and non-parathyroid mediated hypercalcemia, especially when refractory to treatment." (PMID 41246773, 2025).
Hypercalcemia (continued). "Few population-based studies have examined the incidence of subclinical hyperparathyroidism in healthy population, as PTH values are rarely measured without hypercalcemia or symptoms." (PMID 40709988, 2025). "In our patient, common causes of AP, including alcohol abuse and cholelithiasis, were absent, while severe hypercalcemia and elevated PTH were evident." (PMID 41272807, 2025). "In general, hypercalcemia is classified into two categories, PTH-mediated and non-PTH-mediated, depending on serum PTH levels." (PMID 40610015, 2025). "In KTRs, use is mainly pragmatic for persistent PTH autonomy with hypercalcemia, as evidence for bone endpoints is lacking." (PMID 41303180, 2025). "A retrospective study of 56 asymptomatic PHPT patients, having no traditional and specific symptoms or signs of hypercalcemia or PTH excess, showed that PHPT adversely affects bone geometry." (PMID 40177730, 2025). "It typically presents with a triad of symptoms: lifelong non-progressive hypercalcemia, normal or mildly elevated parathyroid hormone (PTH) levels, and hypocalciuria." (PMID 40070587, 2025). "Independent predictors of reintervention included absence of concomitant thymectomy, preoperative hypercalcemia, fewer visualized glands preoperatively, and preoperative PTH > 2000 pg/mL." (PMID 40725638, 2025). "The biological father was diagnosed with asymptomatic hypercalcemia with elevated PTH at age 48, and despite partial parathyroidectomy (no adenoma present), hypercalcemia persisted." (PMID 41311753, 2025). "Hypercalcaemia workup, including parathyroid hormone (PTH), vitamin D, myeloma screen, and imaging, revealed no underlying malignancy or granulomatous bone involvement." (PMID 41216250, 2025). "In our patient, mild hypercalcemia with progressive hypophosphatemia with elevated PTH levels was noted; however, she did not have increased urinary calcium secretion, otherwise characteristic of primary hyperparathyroidism." (PMID 40357201, 2025). "Another case involved marked elevation of serum IgG4 with polyclonal hypergammaglobulinemia and hypercalcemia, accompanied by low PTH and 25(OH)D, but without histopathological confirmation." (PMID 41451224, 2025). "Here, we report a rare case of a six-month-old girl of consanguineous parents with symptoms related to these diseases, including failure to thrive, nephrocalcinosis, hypercalcemia, hypophosphatemia with low TRP, elevated levels of 1,25-(OH)2D3, and suppressed PTH." (PMID 40943461, 2025). "By emphasizing the correlation between hypercalcemia and PHPT in hyperthyroid patients, we reinforce the necessity of routine calcium and PTH screening in this population, which may help reduce diagnostic delays." (PMID 40224187, 2025). "Unlike PTH-driven hypercalcaemia, this mechanism is independent of feedback regulation, which can result in persistent elevation of calcium levels." (PMID 40709165, 2025). "We present the case of an 84-year-old woman with severe parathyroid hormone-independent hypercalcemia and elevated 1,25-OH Vitamin D. Non-necrotizing granulomas were identified on bone marrow biopsy." (PMID 41024908, 2025). "Studies suggest that hypercalcemia occurs in 8-15% of patients receiving lithium for bipolar disorder, while elevated PTH levels without concurrent hypercalcemia have been reported in 15-47% of cases." (PMID 40851725, 2025). "Other laboratory findings: Comprehensive hypercalcemia workup revealed non-suppressed PTH, with high-normal intact PTH of 43.3 pg/mL (ref 8.7–77.1 pg/mL)." (PMID 41227076, 2025). "Serum Li concentration, but not the duration of Li use, exhibited a statistically significant positive correlation with hyper PTH levels (p=0.044) and hypercalcemia (p=0.047); this correlation was independent of other factors." (PMID 40747083, 2025).
Hypercalcemia (continued). "The resulting fluctuations in PTH levels ultimately reflects the antagonistic effect of tumor-induced hypercalcemia, which intermittently suppresses PTH secretion through negative feedback, producing a cyclical pattern." (PMID 41561737, 2025). "In such patients, chronic reductions in calcitriol synthesis, phosphate retention, and reduced sensitivity of calcium-sensing receptors often lead to elevated baseline PTH levels that are not fully suppressed, even in the face of acute hypercalcemia." (PMID 40305356, 2025). "The Epfn KO, MEM1 cKO, and PTH‐CyclinD1 TG mouse models are associated with hypercalcemia, while the CaSR, Cyp27b1, and VDR KO mouse models have a normal serum calcium level despite elevated PTH due to impaired calcium absorption in the kidneys and intestine." (PMID 40164571, 2025). "Key differentiating features between IH and PHPT include a consistently high PTH level, lack of PTH suppression during the calcium infusion test, and the ineffectiveness of oral etidronate for hypercalcemia management." (PMID 40109792, 2025). "The diagnosis is confirmed on the basis of PTH elevation recorded on at least two occasions, in the absence of hypercalcemia (normal total serum calcium and ionic calcium)." (PMID 39582410, 2025). "The rate of P reabsorption to adjust plasma P levels may involve Na/P co-transport activity through hormonal control such as PTH and vitamin D, but may also be effectively regulated by STC1, which enhances renal P reabsorption and prevents hypercalcemia." (PMID 39930376, 2025). "In metastases, hypercalcemias of malignancy can be observed, but elevations of PTH are almost never seen." (PMID 38795187, 2024). "However, living donor KTRs showed a significantly higher rate of PTH normalization and an overall significantly lower percentage of patients with HPT and hypercalcemia at all follow-up time points." (PMID 39001249, 2024). "In patients with persistent PTH-elevation but no hypercalcemia, calcimimetics were given in 4.9% at 12 months and 4.6% of patients at the 24-month follow up." (PMID 39001249, 2024). "Active vitamin D preparation administration is indicated for patients with high serum intact PTH levels without hypercalcemia." (PMID 38713253, 2024). "Together, these data indicate that deletion of Cyp24a1 from the intestine is sufficient to augment local 1,25D effects and suppress PTH without precipitating hypercalcemia or altering systemic vitamin D levels." (PMID 39688907, 2024). "Hypercalcaemia, defined as elevated serum calcium levels, often prompts an evaluation of parathyroid hormone (PTH) levels to differentiate between parathyroid-related and non-parathyroid-related hypercalcaemia." (PMID 39434928, 2024). "Shortened QTc normalized while on cinacalcet in the first patient and reductions in serum calcium and PTH levels without symptomatic hypercalcemia were noted in the second patient." (PMID 38832006, 2024). "However, with the advent of PTH assays, PHPT is now more easily diagnosed, and severe symptomatic hypercalcemia is becoming rare." (PMID 39588408, 2024). "Renal CYP27B1 is stimulated by the parathyroid hormone (PTH), hypocalcemia and hypophosphatemia and receives negative feedback from 1,25(OH)2D3 as well as hypercalcemia." (PMID 39337491, 2024). "The aim of our study was to evaluate vitamin D status in patients with confirmed autonomous PTH secretion with or without hypercalcemia to assess the impact of different 25(OH)D levels and the high PTH on bone health and biochemical changes." (PMID 39040613, 2024). "Until 2022, patients in the public health systemwere not allowed to receive cinacalcet unless they had a serum PTH higher than 800pg/mL or persistent hypercalcemia or hyperphosphatemia and a documented failure toachieve adequate PTH levels with VDRAs17." (PMID 38039492, 2024). "Initial tests for evaluating hypercalcemia should include PTH levels to differentiate between PTH-related and non-PTH-related hypercalcemia." (PMID 39559636, 2024).
Hypercalcemia (continued). "This is especially relevant to NCPHPT and secondary hyperparathyroidism, in which hypercalcemia is not a feature and the diagnosis is reliant on elevated PTH level." (PMID 38292595, 2024). "In a high rate of patients with secondary HPT and hypercalcemia at the time of transplantation, either both PTH and calcium normalized (no HPT), or calcemia alone normalized with persistently elevated PTH." (PMID 39001249, 2024). "Vitamin D and analogs were prescribed very frequently (62.5–88.6%) in all patients at the KT, as well as at the 12- and 24-month follow up, independent of PTH-levels or the presence of hypercalcemia." (PMID 39001249, 2024). "Here we show minimal xenograft growth, lack of xenograft involvement in the RAAS pathway, and PTH-independent hypercalcemia and hypophosphatemia after kidney xenotransplantation." (PMID 37311769, 2023). "In contrast, PTH was suppressed in 100% (6/6) of animals after transplant (P < 0.001) as an appropriate response to hypercalcemia and no PTHrP was ever detected." (PMID 37311769, 2023). "Patients with parathyroid cancer often have severe hyperparathyroidism, and elevated serum parathyroid hormone (PTH) levels (> tenfold), which leads to marked hypercalcemia and clinical symptoms such as fatigue, bone complications, renal manifestations, and cardiac arrhythmia." (PMID 37424030, 2023). "For instance, the anabolic effects of PTH are not sustained after therapy discontinuation, and hypercalcemia is among the side effects reported, possibly due to the off-target effects of PTH." (PMID 37232969, 2023). "However, hypophosphatemia and hypercalcemia frequently occur after KT because of persistent elevations in FGF23 and parathyroid hormone (PTH) levels in the early phase after a successful KT15–17." (PMID 37949967, 2023). "Clinicians should maintain a high index of suspicion for parathyroid carcinoma when evaluating patients with primary hyperparathyroidism, especially if there are palpable masses or atypical imaging findings alongside elevated parathyroid hormone (PTH) and hypercalcemia levels." (PMID 40729208, 2023). "Generally, the relationship between PTH and calcium was stronger in the setting of hypercalcemia (≥ 2.5 mmol/L) using most of the formulae regardless of vitamin D level." (PMID 37251673, 2023). "The four patients with HCINF3 showed reductions in 1,25(OH)2D and urinary ca:cr after 10 mg/kg/d, but hypercalcemia did not improve and there were variable responses in 1,25(OH)2D/PTH ratios." (PMID 36990163, 2023). "This milder form of the disease is characterized by hypercalcemia accompanied by both upper-normal or elevated PTH, albeit without any discernible symptoms." (PMID 37370696, 2023). "In the early 2000s, NPHPT was recognized as a new entity of PHPT with elevated PTH levels in the absence of hypercalcemia." (PMID 38115826, 2023). "Case 1 presented with hypercalcemia and medullary nephro-calcinosis with multiple nonobstructing renal stones with mildly elevated PTH, and the patient died before rechecking it." (PMID 37264371, 2023). "The majority of cases were assessed as having hypercalcaemia due to immobilisation in the setting of low to normal parathyroid hormone levels, no suspicion of malignancy, and absence of other possible causative factors." (PMID 37680410, 2023). "A PHTP diagnosis is established when there is hypercalcemia accompanied by inappropriate PTH suppression (values are normal or high)." (PMID 37653552, 2023). "In the preoperative work-up, all patients had a high level of PTH (median 432 pg/mL, IQR 296.5 – 877) and hypercalcemia (median value 11.20 mg/dL, IQR 11-14.30) except for one female patient with a value of 8.8 mg/dL, whose PC was discovered during a total thyroidectomy for a thyroid goitre." (PMID 38027123, 2023).